EPHA1 (EPH receptor A1)
Diseases named in the same sentence as EPHA1 in open-access papers (continued):
Sharing a sentence is not in itself a finding about the gene and the disease.
adenocarcinoma (2 papers, 2014 to 2025). A common cancer characterized by the presence of malignant glandular cells. "In regards to 11 kinases specifically regulated in AD, siRNA‐mediated gene‐silencing of CDK1, EPHA1, JAK3, RET and ZAP70 caused loss of cell viability in a panel of six human adenocarcinoma cell lines." (PMID 39995112, 2025). "Of the 56 adenocarcinoma-type NSCLC cases, moderate/high EphA1, A4, A5 and A7 expression was noted in 9 (16.1%), 13 (23.2%), 35 (62.5%) and 33 (58.9%), respectively." (PMID 24495444, 2014).
infection (1 paper, 2020). The state of being infected such as from the introduction of a foreign agent such as serum, vaccine, antigenic substance or organism. "A comparison of the transcriptional profile of the EphA receptor subfamily in whole brain tissue isolated from mice infected with PbA revealed a significant upregulation of EphA2 transcript at day 6 post-infection at the onset of ECM symptoms along with a slight upregulation of EphA1 transcript." (PMID 31999807, 2020).
lymph node (1 paper, 2014). "EPHA1 protein levels showed significant associations with clinicopathological parameters, whereupon patients with an absent EPHA1 immunoreactivity frequently had a lower grade (p<0.001) and absent lymph node metastases (p = 0.015)." (PMID 25025847, 2014).
EPHA1 also shares sentences with these, for which no sentence is quoted: dementia (2 papers); non-melanoma skin carcinoma (2); acute promyelocytic leukemia (1); amyotrophic lateral sclerosis (1); Apathy (1); autism (1); cervical cancer (1); colon cancer (1); embryonal rhabdomyosarcoma (1); esophageal cancer (1); esophageal squamous cell carcinoma (1); familial Alzheimer disease (1); gastric tumor (1); hematologic malignancies (1); hippocampal atrophy (1); Hypertension (1); ischemia (1); kidney cancer (1); liver cancer (1); medullary sponge kidney disease (1); metastatic disease (1); neurological disease (1); oral cancer (1); osteosarcoma (1); pancreatic cancer (1); skin tumor (1); soft tissue sarcoma (1); squamous cell lung carcinoma (1); vascular dementia (1).